IL5 (interleukin 5)
Diseases named in the same sentence as IL5 in open-access papers (continued):
Sharing a sentence is not in itself a finding about the gene and the disease.
asthma (continued). "Chronic rhinosinusitis with nasal polyposis may be observed in patients with asthma and eosinophilic granulomatosis with polyangiitis (EGPA), and as such, has also been taken into consideration in clinical trials testing efficacy of anti-IL-5 in these disorders." (PMID 29682504, 2018). "However blocking IL-5 alone is not sufficient to decrease asthma severity." (PMID 28721208, 2017). "Nevertheless, Th2 cytokines expression levels (IL-4, IL-5 and IL-13) and miRNA expression profile were similar in AR patients with and without asthma, suggesting that concomitant asthma might have a minor impact on the inflammatory profile and miRNA expression of AR patients." (PMID 27187364, 2016). "Moreover, previous studies have shown that eosinophilic inflammation could not be developed in the absence of IL-5, and it was shown that IL-5 signaling in the airways was necessary for the development of asthma in allergic mice." (PMID 24489937, 2014). "However the fact that IL-13, like IL-5, is not increased in non eosinophilic asthma indicates that these Th2 cytokines are essentially related to a peculiar inflammatory profile rather than to asthma itself." (PMID 23555579, 2013). "If a patient has severe asthma or did not benefit from ICS medications, further treatments including biological agents which act on IL-5 (mepolizumab, reslizumab), IL-4/IL-13 (dupilumab) or IgE (omalizumab) can be used." (PMID 40662069, 2025). "As for the Th2 biomarkers(IL-4 P=0.142, IL-5 P=0.4791, IL-13 P=0.6885, Serum IgE P=0.2534, TARC P=0.2074, TSLP P=0.6571), there are no significant statistical differences observed between asthma and control subjects." (PMID 40503233, 2025). "IgE level did not correlate with IL-5 or eotaxin-3 concentrations or the expression of CD193 on sputum and blood eosinophils in asthma, COPD or control subjects." (PMID 37371101, 2023). "Second, because anti-IL-5/IL-5Rα mAbs alone have not yet been approved for ABPA treatment, this study was limited to patients with comorbid asthma." (PMID 37015988, 2023). "Probiotic and prebiotic treatments reduced the levels of Th2 cytokines (IL-4, IL-5, IL-13, IL-17, IL-25, and IL-33) and increased IFN-γ level in the BALF of asthmatic mice as compared to the non-treated asthma group." (PMID 35296330, 2022). "Another notable similarity between these studies is that exogenous leptin administration did not alter BAL eosinophil levels induced by the respective asthma models, but exogenous leptin did significantly decrease BAL IL-5 levels." (PMID 35610699, 2022). "IL-5 levels were significantly elevated in NOA patients with respect to HC and O subjects without asthma." (PMID 35807067, 2022). "Other classically recognized T2 cytokines, IL‐4 and IL‐5, were not significantly elevated in the BAL of severe asthma patients compared to healthy controls." (PMID 33411348, 2021). "Since only IL-13 (but not IL-4 or IL-5) expression was diminished in Cd2−/− HDME mice, our data demonstrate a specific regulation of IL-13 by CD2 in asthma." (PMID 32477356, 2020). "Asthma endotypes are often clustered TH2 high or TH2 low, based on the presence or absence of eosinophils and IL-4, IL-5 and IL-13 cytokines in BAL, all of which we found increased following HDM challenge." (PMID 32038643, 2019). "ND mice with OVA-induced asthma had high-expression levels of IL-4 and IL-5, but naive HFD mice did not express significantly higher IL-4 or IL-5 levels in the lung tissue than naive ND mice." (PMID 31133649, 2019). "IL-5 levels differed significantly between the PBMC culture and P+S coculture in the nonasthma (P < 0.05) and asthma groups (P < 0.05)." (PMID 31673233, 2019). "The IL-5-producing capacity of CD4+ T cells is higher in both atopic and nonatopic patients with asthma." (PMID 31216735, 2019). "Even though BAL eosinophil % in all subjects with asthma correlated with BAL fluid IL-5 levels, neither eosinophil % nor IL-5 levels correlated with % predicted FEV1." (PMID 26011707, 2015).
asthma (continued). "Recently, children (5–17 years) with severe therapy-resistant asthma had significantly increased BAL eosinophils compared control subjects but no increase in BAL fluid interleukin (IL)-4, IL-5, or IL-13 levels." (PMID 25905006, 2014). "In contrast, Th2 cytokines (IL-4, IL-5, and IL-13) are not elevated, suggesting that AHR in this model is not Th2-mediated, contrary to AHR in asthma models." (PMID 24844383, 2014). "In the acute asthma model, we found a 55% reduction in IL-4 transcripts in the OVA-treated sPLA2-X knockout mice but no decrease in IL-5 or IL-13 transcripts." (PMID 23451035, 2013). "Since we do not detect genotype-specific differences in mRNA degradation of IL-4 or IL-13 in polyclonally stimulated CD4+ T cells and no degradation of IL-5 mRNA, modulation of mRNA stability by KSRP does not appear to be the main reason for the effects observed in our asthma model." (PMID 40095032, 2025). "Even though most data come from studies in which patients suffer both from asthma and CRS, there are studies showing the effectiveness of anti-IL-5 treatment regardless of asthma, with patients benefiting from symptom relief, reduced corticosteroid use, and improved quality of life." (PMID 39062104, 2024). "The first study found that 13-year-old children who reported higher levels of parental support were less resistant to hydrocortisone’s anti-inflammatory effects on stimulated IL-5 and IFN-γ if they had asthma, while this effect was not seen in healthy controls." (PMID 34347228, 2023). "Third, previous meta-analyses concluded that anti-IL-5-targeted therapy significantly reduced moderate-to-severe exacerbations in COPD, but our integrated analysis of two doses demonstrated that the doses approved for severe asthma were not sufficient." (PMID 35756113, 2022). "A correct definition of asthma and CRS phenotype/endotype is crucial, taking into account the availability of novel biological therapies, such as anti-IgE, anti-IL-5/IL-5Rα and anti-IL4/IL-13Rα, which are dedicated to patients who do not respond to conventional asthma or CRSwNP therapies." (PMID 33805199, 2021). "However, simple exposure to 1 μg LPS without asthma induction (LPS/PBS) did not significantly affect Foxp3, GATA3, or ROR-γt mRNA levels nor IL-10, TGF-β, IL-4, IL-5, IL-13, or IL-17 levels (p > 0.05) compared to those of Control mice." (PMID 33072079, 2020). "In this study, the levels of miR-1 and the Th1-expressed cytokine IFN-γ in peripheral blood of children with acute-stage asthma were significantly lower, whereas the expression levels of the Th2 cytokines IL-4, IL-5, IL-8, and TNF-α were significantly higher than levels in children without asthma." (PMID 30046607, 2018). "Another mouse model of asthma revealed that a CCR3 monoclonal antibody could significantly suppress airway eosinophilia and mucus production without decreasing IL-5 levels in BALF." (PMID 27275740, 2016). "Due to the small number of respondents with IL-5 responses to HDM stimulation at age 3 years, it was not possible to directly test the hypothesis that HDM avoidance was more effective at preventing asthma in this sub-group." (PMID 24875149, 2014). "Traditional markers of asthma such as FEV1 and the acute bronchodilator response may not be related to the efficacy of anti–IL-5, while existing data suggested the pathogenesis of asthma exacerbation appear to be correlated with eosinophilic inflammation." (PMID 23544105, 2013). "This IL-5 concentration is presumably low, since it does not result in significant expression of the mAb24 and CBRM1/5 epitopes in fully activated αMβ2; and the IL-5 concentration in the blood of subjects with asthma is only 1–10 pg/ml (0.04–0.4 pM)." (PMID 23554594, 2013).
asthma (continued). "It is also supported by the experimental evidence thatmucosal gene transfer of IL-12 via a vaccinia virus vector inhibited theability of lung lymphoid cells to produce IL-4 and IL-5, but not IFN-γand prevented the development of airway hyperreactivity in a mouse model ofovalbumin-induced asthma." (PMID 19381339, 2009). "Moreover, data comparing IL‐5 levels in patients with T2 severe asthma and eosinophilic COPD are lacking; hence, it can be speculated that patients with COPD could have a lower baseline IL‐5 production compared to asthmatic patients." (PMID 40492692, 2025). "Of particular significance is the potential for eosinophils and FeNO to serve as biomarkers of IL-5, IL-4Ra, or TSLP-driven inflammation, as these cytokines may constitute targets for future biological therapies, regardless of the co-existence of asthma or COPD." (PMID 40589741, 2025). "Interestingly, even though levels of IL-5 and IL-13 were increased in the media of ILC2 culture from Hps1−/− mice, levels of eosinophilia and eotaxin expression were comparable, and no asthma-related phenotypes were observed in these mice after bleomycin challenges." (PMID 39405112, 2024). "However, while the 3 mg protein/ml SHE solution did not induce asthma, co-exposure with DEP resulted in a markedly enhanced AHR (p = 0.002) and eosinophilic inflammation (p = 0.004), with increased levels of IL-5, IL-17F and CCL20 and decreased levels of IFN-γ." (PMID 28628664, 2017). "However, this bias was not seen in patients with severe asthma, in whom frequencies of IL-13–secreting TH2 cells were not significantly different from those in healthy subjects, although we did not measure frequencies of IL-4– or IL-5–secreting T cells." (PMID 25746968, 2015). "We tested this hypothesis by comparing plasma cytokines, including IL-2, IL-5, IL-10, IL-13, IL-17A, IL-22, IL-33, IFN-γ, and TNF-α and the adipokine, leptin in normal weight and overweight/obese children, both with and without asthma in a cross-sectional study." (PMID 39902293, 2024).
eosinophilia (690 papers, 1995 to 2026). "The Th2 cells and their cytokines, interleukin-4 (IL-4) and interleukin-5 (IL-5), promote the production of IgE and eosinophilia, which are critical components of the atopic predisposition." (PMID 40831866, 2025). "A key difference between dupilumab and the mAbs targeting IL-5 is that dupilumab can cause transient eosinophilia in a fair percentage of patients, from 4% up to 25%." (PMID 40869013, 2025). "Most eosinophilia is reactive, caused by an overproduction of eosinophilopoietic cytokines such as interleukin 3 (IL-3), interleukin 5 (IL-5), or granulocyte-macrophage colony stimulating-factor (GM-CSF)." (PMID 40567444, 2025). "It challenges the traditional view that cancer-associated eosinophilia is limited to hematologic malignancies and underscores the role of tumor-derived cytokines like IL-5 in driving systemic inflammation and end-organ damage." (PMID 41398896, 2025). "These chemokines are induced by Th2 cytokines (IL-4 and IL-13) and work synergistically with IL-5 to drive eosinophilia, a hallmark of helminth infections." (PMID 40872306, 2025). "This reasoning, along with scientific rationale, underlies the fact that the highest baseline blood eosinophilia was present in participants on anti-IL-5 therapy." (PMID 40047156, 2025). "It explores the underlying mechanisms of eosinophilia in these malignancies, highlighting the role of chemokines and cytokines such as IL-5, TARC, and eotaxin." (PMID 39873807, 2025). "The cytokines such as IL-4, IL-5, and IL-13 are released causing eosinophilia and the pro-inflammatory cytokines like IFN-γ, TNF, IL-6, and IL-15 are increased promoting systemic inflammation." (PMID 41229508, 2025). "Th2-associated cytokines, including interleukin (IL)-5 and IL-13, are frequently elevated in eosinophilic adenoidal or sinonasal inflammation, correlating with tissue eosinophilia, goblet cell metaplasia, and corticosteroid responsiveness." (PMID 40868875, 2025). "Gain-of-function mutations in STAT3, for example, have been linked to dysregulated cytokine signaling and enhanced IL-5 production, potentially worsening eosinophilia." (PMID 41488087, 2025). "SNPs identified in this gene are strongly associated with IL-5 levels and eosinophilia, potentially influencing the therapeutic response." (PMID 39125709, 2024). "Elevated levels of IL-4, IL-5, and IL-13 are noted in patients and are associated with increased peripheral eosinophilia and IgE levels, which are common features of this disease." (PMID 39139309, 2024). "T-bet deficiency results in the loss of IFN-γ production, and in turn is linked to the excessive production of IL-5 and IL-13 by Th2 cells, leading to the development of upper airway allergic inflammation and eosinophilia." (PMID 37727514, 2023). "In Western societies, nasal polyps are predominantly the consequence of a Th2 cell-driven eosinophilia, IgE inflammation and raised IL-5, often associated with environmental and/or seasonal allergic triggers." (PMID 37375083, 2023). "In ovalbumin-induced asthma, γδ-T cell-deficient mice had reduced AHR, airway eosinophilia, peribronchial lymphocytic infiltration as well as lower serum IgE and lung IL-5 levels compared to wild-type mice." (PMID 36305904, 2022). "Further divisions are based on the anatomic distribution (localized or diffuse disease), endotype dominance (understanding the underlying pathophysiology in association with raised IgE, IL-5, eosinophilia, and periostin), and clinical phenotypes." (PMID 36291990, 2022). "This exposure was associated with increased levels of total IgE, asIgE, IL‐4, IL‐5 in blood and nasal eosinophilia as determined by histological examination." (PMID 34965026, 2022). "Increased airway sensory innervation is present in patients with eosinophilic asthma and in mice that overexpress IL-5 in airway epithelium, causing airway eosinophilia." (PMID 36107629, 2022).
eosinophilia (continued). "Th2 cells are classically regarded as important effector cells that produce the hallmark cytokines IL-4 and IL-13, but also IL-3 and IL-5 that promote basophilia and eosinophilia, respectively." (PMID 35844529, 2022). "Our results agree with a previous report that IL-5 is a key cytokine in nasal polyposis and it is strongly associated with eosinophilia." (PMID 36013200, 2022). "Fungi-induced production of eosinophilia-associated cytokines, such as IL-5 and IL-13, from nasal mucosa and epithelial cell-derived cytokines, the initiating mediators of type 2 immune responses." (PMID 36362100, 2022). "Of these, IL‐5 and IL‐13 are hallmark cytokines of type 2 inflammation, involved in eosinophilia, smooth muscle cell contraction and mucus secretion, and TNF is important in several inflammatory diseases." (PMID 34873877, 2022). "This was disappointing given the central role that IL-5 plays in eosinophilia and the clear association between eosinophils and several asthmatic phenotypes." (PMID 34739571, 2021). "MF and SS have been associated with a Th 2 cytokine milieu including elevated IL-5 expression leading to eosinophilia in skin and peripheral blood." (PMID 34097126, 2021). "For instance, the IL-33/ST2 axis is associated with bone marrow ILC2s and IL-5-dependent eosinophilia." (PMID 34177881, 2021). "Eosinophils play a central role in the EGPA pathophysiology with blood and tissue eosinophilia as the disease hallmark; IL-5 is recognized as the key mediator in the development and maintenance of this pathogenic finding." (PMID 34640595, 2021). "As Th2-mediated responses that underlie airway eosinophilia and airway hyperresponsiveness have been linked to IL-4, IL-5, and IL-13, we measured the levels of these cytokines in the BAL of OVA-exposed mice." (PMID 34744763, 2021). "Extrinsic, reactive forms of eosinophilia are the most common ones caused by cytokines such as IL-3, IL-5, and GM-CSF that are released by mainly T cells, as well as tumor cells." (PMID 34097126, 2021). "Anti-ICAM-1-treated mice showed lower lung ILC2s, lower BAL eosinophilia associated with a decrease in ILC2-dependent IL-5 and IL-13 expression compared to controls." (PMID 33193309, 2020). "Second, we did not measure the markers that influenced eosinophil activity, such as IL-3, IL-5, and GM-CSF, and were unable to identify the association between eosinophilia and the extent of eosinophilic inflammation." (PMID 32266635, 2020). "IL-5, eosinophilia and exacerbations are closely linked, therefore, the effect of mepolizumab on yearly exacerbation rates has been extensively studied." (PMID 31395084, 2019). "Previous studies have reported IL-5-induced eosinophilia associated with IL-2/JES6-1 immunocomplex treatment in a murine model of dermatitis as well as in cancer patients that received high- or low-dose IL-2 immunotherapy." (PMID 30930900, 2019). "In an aluminum hydroxide/ovalbumin-sensitized mouse asthma model, IL-5 deficiency abolished eosinophilia." (PMID 29751492, 2018). "Differences in CRS inflammatory profile types have been observed previously between different populations globally, including an increased association between polyposis and eosinophilia and IL-5 in European populations compared to patients studied in China." (PMID 30283438, 2018). "IL-5 and IL-13 cause eosinophilia and smooth muscle cell contraction respectively, altogether contributing to the pathogenesis of asthma." (PMID 30524437, 2018). "A wealth of evidence support a critical role for the cytokine IL-5 in mediating disease-associated eosinophilia, and neutralizing IL-5 indirectly suppresses eosinophil maturation." (PMID 28791289, 2017). "Eosinophilia in bullous pemphigoid patients is likely caused by increased levels of IL-5, which can be detected at high levels in the serum and blister fluid." (PMID 28496445, 2017).